POSTN (periostin)
Diseases named in the same sentence as POSTN in open-access papers (continued):
Sharing a sentence is not in itself a finding about the gene and the disease.
schwannoma (2 papers, 2015 to 2025). A benign, usually encapsulated slow growing tumor composed of Schwann cells. "Other notable ECM-related genes include that we identified in our analysis with less evidence in schwannoma included: ITGA1, POSTN, SPP1, ID3, ADAMTS6." (PMID 40585242, 2025). "Furthermore, in a recent NF2 genetically engineered mouse model, generated through excision of the NF2 gene driven by Cre expression (restricted to periostin promoter element), the NF2 mice developed multiple schwannomas in peripheral and cranial nerves." (PMID 26104281, 2015).
serous ovarian cancer (2 papers, 2020 to 2021). "When we looked at periostin expression in cancer cells, we observed that all early stage serous ovarian cancers (FIGO I-II) showed strong staining, while some percentage of FIGO III-IV and metastatic samples showed weak staining." (PMID 31936272, 2020).
steatosis (2 papers, 2020 to 2022). Increased lipid within the cytoplasm of cells. "In contrast, other investigations failed to report dexamethasone-induced triglyceride accumulation in cultured hepatocytes, thus leading to the proposal that corticosteroid-induced steatosis in vivo requires some systemic factors such as NEFAs or periostin." (PMID 35162986, 2022). "Dexamethasone-induced steatosis in mice was almost fully prevented by the administration of a periostin-neutralizing antibody or in periostin-knockout mice." (PMID 35162986, 2022).
tendinopathies (2 papers, 2014 to 2022). "Periostin is upregulated in tendinopathy, and in this study was found to be enriched in ACL." (PMID 24818782, 2014). "Periostin may be a candidate to treat tendinopathies such as Osgood–Schlatter disease." (PMID 35888676, 2022).
type 2 diabetic nephropathy (2 papers, 2015 to 2020). "The study included 30 healthy volunteers and 328 type 2 diabetic nephropathy patients with normal proteinuria (n = 114), trace proteinuria (n = 100) or massive proteinuria (n = 114), using an enzyme-linked immunosorbent assay to determine urine periostin content." (PMID 33241962, 2020). "Recently, a clinical study evaluated the clinical significance of urine periostin to patients with type 2 diabetic nephropathy." (PMID 33241962, 2020). "Taken together, these data demonstrate that periostin is a likely marker of renal tubular injury and a promising renal tissue and urine biomarker for kidney injury in early stages of type 2 diabetic nephropathy." (PMID 25884625, 2015).
urothelial carcinoma (2 papers, 2022 to 2023). A malignant neoplasm derived from the transitional epithelium of the urinary tract (urinary bladder, ureter, urethra, or renal pelvis). "This feature, suggesting a possible protective role of POSTN secreted by CAFs with the aim of containing the neoplastic infiltration, was also noted in a recent study on human urothelial carcinomas, even if the research was focused on the tumor affecting the upper urinary tract." (PMID 38076555, 2023). "Periostin overexpression in cancer cells and/or intervening stroma is usually related to tumor progression and poor patient outcomes in various human cancers; however, its role in urothelial carcinoma, especially upper urinary tract urothelial carcinomas (UTUCs), remains inconclusive." (PMID 35850759, 2022).
abortion (1 paper, 2024). the ending of pregnancy by removing a fetus or embryo before it can survive outside the uterus. "In addition, periostin levels have been found to vary in cases of spontaneous abortion compared with voluntary abortions, suggesting a potential role for periostin in early pregnancy maintenance." (PMID 39045965, 2024).
acid reflux (1 paper, 2025). "Background/Objectives: In children, gastroesophageal reflux disease (GERD) may lead to epithelial barrier dysfunction and the release of thymic stromal lymphopoietin (TSLP), interleukin-25 (IL-25), interleukin-33 (IL-33) and periostin, known as alarmins." (PMID 40981017, 2025).
acral lentiginous melanoma (1 paper, 2019). A form of melanoma occurring most often on the plantar, palmar, subungual, and periungual skin. "We then immunohistologically examined the expression of stromal periostin and the infiltration of CD163+ M2 macrophages in human acral lentiginous melanomas (n = 94) and analyzed the statistical associations with clinicopathological variables." (PMID 30621220, 2019).
acute myeloid leukemia (1 paper, 2022). Acute myeloid leukemia (AML) is a group of neoplasms arising from precursor cells committed to the myeloid cell-line differentiation. "In the MLL-AF9 acute myeloid leukemia (AML) in vivo model, it has been shown that CSCs express periostin and its receptor, integrin, in secondary target tissues indicating the autocrine and paracrine effects of periostin on CSCs behavior such as invasion and metastasis." (PMID 36224629, 2022).
age (1 paper, 2023). A temporal measurement of the time period elapsed since an identifiable point in the life cycle of an organism. "In addition, population-based studies are needed to shed further light on the potential role of plasma POSTN and other MPs (such as osteopontin and thrombospondin, tightly related to age-related fibrosis process) as transversal markers of healthy/accelerated aging." (PMID 36373873, 2023).
alcohol abuse (1 paper, 2024). The use of alcoholic beverages to excess, either on individual occasions ("binge drinking") or as a regular practice. "Expression of FAP, α-SMA, PDGFRb or periostin was independent from nicotine or alcohol abuse, UICC stage, sex or HPV status." (PMID 38328551, 2024).
allergic respiratory disease (1 paper, 2021). A respiratory system disease with a basis in a pathological type I hypersensitivity reaction. "While some studies show that periostin plays a protective role in allergic respiratory diseases, one study using periostin homozygous mutant mice seems to implicate a reduction in airway allergic reactions in the absence of periostin." (PMID 34512647, 2021).
alopecia (1 paper, 2025). Hair loss usually from the scalp. "Elevated POSTN expression has been associated with scarring alopecia." (PMID 40565255, 2025).
Alzheimer disease (1 paper, 2023). A progressive, neurodegenerative disease characterized by loss of function and death of nerve cells in several areas of the brain leading to loss of cognitive function such as memory and language. "First, proteomics screening and statistical analysis show that blood biomarkers LGALS3BP, ACE, and POSTN effectively screen for cerebral amyloid depositions and clinically diagnose Alzheimer’s disease, but the theoretical basis is still lacking." (PMID 37446296, 2023).
aneurysm (1 paper, 2025). Bulging or ballooning in an area of an artery secondary to arterial wall weakening. "In this study, we found that non‐BM‐derived CD34+ cells function as fibroblast progenitor cells to generate Periostin+ myofibroblasts, which participate in the formation of the adventitial fibrous collar of the aneurysmal aorta, thereby restricting aneurysm development." (PMID 39731355, 2025). "CD34+ cells actively contribute to the formation of a fibrous collar around the aneurysmal aorta by generating Periostin+ myofibroblasts, which may enhance the biomechanical strength to protect the aneurysm from rupture." (PMID 39731355, 2025). "Collectively, although both PDGFRs in CD34+ cells play important roles in CD34+ cell proliferation and AAA progression, PDGFRb, rather than PDGFRa, is required for CD34+ cell transdifferentiation into Periostin+ myofibroblasts, thereby protecting aneurysms from rupture." (PMID 39731355, 2025).
ankylosis (1 paper, 2025). Fixation and immobility of a joint. "Periostin's rapid disappearance following avulsion likely creates permissive conditions for ankylosis." (PMID 41172499, 2025).
aortic aneurysm (1 paper, 2025). A ruptured aneurysm located in the wall of the proximal portion of the descending aorta proceeding from the arch of the aorta. "Herein, we observed downregulated expression of CD34 in both human and mouse aortic aneurysms and demonstrated that CD34+ cells give rise to Periostin+ myofibroblasts in AAA induced by both angiotensin II (Ang II) infusion and calcium chloride (CaCl2) adventitial application." (PMID 39731355, 2025).
aortic stenosis (1 paper, 2023). Aortic valve stenosis is a aortic valve disease caused by the incomplete opening of the aortic valve. "The role of various proteins present in the ECM, such as proteoglycans and periostin, are thought to be involved in the remodeling of the aortic valve during aortic stenosis (AS), but this is not yet fully understood." (PMID 37048799, 2023).
aortic valve disease (1 paper, 2018). "Alternative Cre drivers, such as Periostin or Nfatc1, that target VICs at different developmental time points, including cells not derived from the Tie2 lineage, may further clarify the contributions of RB1 to aortic valve disease." (PMID 29304157, 2018).
astrocytomas (1 paper, 2019). "Periostin expression was increased in secondary GBMs when compared to R132H IDH1 low-grade astrocytomas." (PMID 31052505, 2019).
basal cell carcinoma (1 paper, 2020). A carcinoma involving the basal cells. "Specifically, we found a population of fibroblasts (fibroblast cluster 1) marked by combined expression of POSTN (Periostin) and MMP11, a marker of fibroblasts in basal cell carcinoma." (PMID 33053333, 2020).
bone marrow fibrosis (1 paper, 2020). "Periostin has also been found to be involved in many other tissues and pathologies, where it primarily seems to be involved in various fibrotic conditions, including sub-epithelial fibrosis in bronchial asthma as well as in bone marrow fibrosis." (PMID 33053838, 2020).
bone metabolic disorders (1 paper, 2024). "It seems that periostin together with OPG may play a compensatory role in response to bone metabolic disorders in patients with PWS." (PMID 39273107, 2024).
brain injury (1 paper, 2022). Acute and chronic (see also brain INJURIES, CHRONIC) injuries to the brain, including the cerebral hemispheres, CEREBELLUM, and brain STEM. "Furthermore, in our cohort, CRP, NLR, and WBC showed a close correlation with admission periostin levels, indicating a possible link between the early immune response and post-ischemic brain injury." (PMID 36010292, 2022).
bronchiolitis obliterans syndrome (1 paper, 2024). A lung disorder that is mainly associated with chronic allograft dysfunction after lung transplantation and that is characterized by inflammation and fibrosis of bronchiolar walls that reduce the diameter of the bronchioles and result in progressive and irreversible airflow obstruction. "The utility of measuring serum periostin levels for predicting the occurrence of bronchiolitis obliterans syndrome (BOS) after lung transplantation remains underexplored." (PMID 39408746, 2024).
bronchopulmonary dysplasia (1 paper, 2017). Bronchopulmonary dysplasia is a chronic respiratory disease that results from complications related to lung injury during the treatment of infant acute respiratory distress syndrome in low-birth-weight premature infants or from abnormal lung development in older infants. "Indeed, this hypothesis is supported by previous work where periostin and TGFBI are reported to have opposite effects in the lung in mouse models of bronchopulmonary dysplasia." (PMID 28750100, 2017).
calcific aortic valve disease (1 paper, 2012). "For example, adult periostin-null mice exhibit disrupted collagen matrix layer and aortic valve calcification, which is also seen in some calcific aortic valve disease in human." (PMID 25383261, 2012).
carcinoma in situ (1 paper, 2022). "The frequencies of tumors with subtype histology, concomitant carcinoma in situ, and positive surgical margins were significantly higher in patients with high stromal periostin expression than in those with low expression (p = 0.016, p = 0.047, and p = 0.043, respectively)." (PMID 35850759, 2022).
Cerebral ischemia (1 paper, 2015). Restriction of arterial blood supply to the brain associated with insufficient oxygenation to support the metabolic requirements of the tissue. "POSTN also has a neuroprotective role in vitro and in vivo during cerebral ischemia." (PMID 25894199, 2015).
chondroblastoma (1 paper, 2018). A benign, chondroid-producing, well-circumscribed, lytic neoplasm usually arising from the epiphysis of long bones. "Clear cell chondrosarcoma, which is considered by some observers to be a malignant form of chondroblastoma, also showed expression of periostin in areas of woven bone formed within the clear cell cartilaginous stroma." (PMID 30202513, 2018). "In chondroblastoma, areas of chondroid matrix, some of which showed evidence of mineralisation, stained focally for periostin." (PMID 30202513, 2018). "Giant cells in GCTB, chondroblastoma and ABC were negative for periostin." (PMID 30202513, 2018).
Cirrhosis (1 paper, 2025). A chronic disorder of the liver in which liver tissue becomes scarred and is partially replaced by regenerative nodules and fibrotic tissue resulting in loss of liver function. "Interestingly, Periostin (POSTN) was both downregulated for cirrhosis compared to NAFLD and cirrhosis compared to healthy, although its overexpression was associated with inflammation, fibrosis, and HCC development, as well as metabolic disorders." (PMID 40489530, 2025).
cognitive deficits (1 paper, 2018). "An injection of periostin into the lateral ventricles of hypoxic-ischaemic rats was recently shown to significantly improve spatial learning and memory, indicating that periostin may reverse cognitive deficits after IS19." (PMID 30082879, 2018).
complication (1 paper, 2023). Any disease or disorder that occurs during the course of, or because of, another disease, treatment, or procedure. "Some studies have shown an increase in serum periostin levels in diabetic vascular complications." (PMID 37919715, 2023).
conjunctivitis (1 paper, 2023). Inflammation of the conjunctiva of the eye. "Their work found significantly high periostin levels in a subject affected by ocular allergies than in allergic patients without conjunctivitis (p < 0.05), with maximal levels in AKC and VKC (p < 0.001)." (PMID 37658939, 2023).
cutis laxa (1 paper, 2018). Cutis laxa (CL) is an inherited or acquired connective tissue disorder characterized by wrinkled, redundant and sagging inelastic skin associated with skeletal and developmental anomalies and, in some cases, with severe systemic involvement. "These proteins included several important ECM components, periostin (POSTN), elastin (ELN), and decorin (DCN); genetic mutations in these proteins are associated with different phenotypes of aging, such as cutis laxa and joint and dermal manifestations." (PMID 30574417, 2018).
cystitis (1 paper, 2025). Inflammation of the urinary bladder. "GelMA hydrogels loaded with periostin promoted urothelial regeneration and M2 macrophage polarization in a cyclophosphamide-induced cystitis model." (PMID 41322853, 2025). "In a murine model of cyclophosphamide-induced cystitis, a GelMA granular hydrogel loaded with periostin promoted urothelial regeneration by upregulating Wingless/Int (Wnt) signaling and polarizing macrophages toward a reparative type-2 macrophage (M2) phenotype." (PMID 41322853, 2025).
developmental dysplasia of the hip (1 paper, 2020). A spectrum of hip abnormalities commonly presenting in infancy involving the relationship between the femoral head and the acetabulum and that includes subluxation or dislocation at rest or upon provocation. "Therefore, we detected the differential expression of POSTN and SOST in BMSCs of SONFH Group patients, and Control Group was patients with traumatic ONFH (TONFH) and developmental dysplasia of the hip (DDH)." (PMID 33409280, 2020).
dystrophinopathy (1 paper, 2022). "Expression levels of periostin are clearly affected by dystrophinopathy-associated changes in the extracellular matrix." (PMID 36362832, 2022).
eosinophilic disease (1 paper, 2021). "With the sequent studies of periostin, there is no deny that periostin has been closely associated with eosinophilic disease." (PMID 32954441, 2021).
eosinophilic granulomatosis with polyangiitis (1 paper, 2018). Eosinophilic granulomatosis with polyangiitis (EGPA), previously known as Churg-Strauss syndrome, is a systemic vasculitis of small-to medium vessels, characterized by asthma, transient pulmonary infiltrates, and hypereosinophilia. "Relationship between serum periostin and disease activity in eosinophilic granulomatosis with polyangiitis." (PMID 30308057, 2018).
Eustachian tube obstruction (1 paper, 2024). "Therefore, by reducing IL-4 and/or IL-13 levels, Dupilumab may inhibit periostin production, thus suppressing inflammation, and consequently improving Eustachian tube obstruction." (PMID 39595049, 2024).
fallopian tube cancer (1 paper, 2022). A primary or metastatic malignant neoplasm that affects the fallopian tube. "Periostin, which is expressed in fallopian tube cancer, may induce cell migration, and promote metastasis to host tissue." (PMID 36536419, 2022). "Periostin was highly expressed in fallopian tube cancer and not in OC cells." (PMID 36536419, 2022).
Fibroadenoma (1 paper, 2014). A benign tumor of the breast characterized by the presence of stromal and epithelial elements. "Decorin was present at higher levels in fibroadenomas than in phyllodes tumors (P = 0.009, Mann-Whitney U test; n = 37, 35), whereas periostin was present at lower levels in fibroadenomas (P = 0.007, Mann-Whitney U test; n = 37, 35)." (PMID 25400079, 2014).
fibroma (1 paper, 2018). A non-metastasizing neoplasm arising from the fibrous tissue. "There was no staining for periostin in chondromyxoid fibroma." (PMID 30202513, 2018).
fracture (1 paper, 2022). "Serum periostin levels were nominally significantly associated with the prevalence of vertebral fracture." (PMID 35327993, 2022). "However, the relationship of POSTN polymorphism and serum periostin to the risk of vertebral fracture has not been explored in clinical settings." (PMID 35327993, 2022).
gastric tumour (1 paper, 2023). "Therefore, we speculate that eCAFs might promote ICB resistance through POSTN-mediated macrophage chemotaxis to gastric tumour tissues." (PMID 37199594, 2023). "After culture for 7 days, qRT-PCR and WB assays showed that the expression of POSTN, FAP, MMP2 and PDGFα in the gastric tumour cell exosome-treated group was gradually increased compared with that in the MSC control group." (PMID 37199594, 2023).
giant cell tumour of bone (1 paper, 2018). "In giant cell tumour of bone (GCTB), there was focal, occasionally strong staining for periostin in the collagenous connective tissue matrix around mononuclear cells." (PMID 30202513, 2018).
Glucose intolerance (1 paper, 2023). Glucose intolerance (GI) can be defined as dysglycemia that comprises both prediabetes and diabetes. "We also evaluated predicted signaling from myofibroblast and preadipocytes to IMs, which showed increased MHC-II, CD99, MIF, periostin, amyloid beta precursor protein (APP), and CSF signaling pathways with glucose intolerance and have been implicated in macrophage polarization." (PMID 37711619, 2023).
Graves’ Orbitopathy (1 paper, 2022). "In this study we investigate periostin in the pathogenesis of Graves’ orbitopathy (GO) using human orbital adipose tissue obtained from surgery and primary cultured orbital fibroblasts in vitro." (PMID 35707463, 2022).
haemorrhagic stroke (1 paper, 2018). "It seems that the uptrend of periostin levels is consistent after onset between ischaemic and haemorrhagic stroke, although the rising speed is different." (PMID 30082879, 2018).
hyperandrogenism (1 paper, 2024). Excessive secretion of androgens from the adrenal glands or gonads. "Elevated periostin levels and chronic inflammation may explain hyperandrogenism." (PMID 39045965, 2024).